CXCL10 (C-X-C motif chemokine ligand 10)
Diseases named in the same sentence as CXCL10 in open-access papers (continued):
Sharing a sentence is not in itself a finding about the gene and the disease.
COVID-19 (continued). "Increased levels of the chemokine CXCL10/IP-10 are also observed in nearly all COVID-19 patients, but unlike moderately diseased patients, in which high IP-10 levels are transient, severely diseased patients maintain elevated levels that are proportional to disease progression." (PMID 34239884, 2021). "Critically ill COVID-19 patients exhibited an increased ratio of white blood cells/lymphocytes and higher plasma levels of C-reactive protein (CRP), IL-2, IL-7, IL-10, GSCF, IP10 (CXCL10), MCP-1 (CCL2), MIP-1α (CCL3), and TNF-α, as compared to non-ICU patients." (PMID 32998763, 2020). "Cytokine storm was observed in severe COVID-19 patients with high levels of various serum cytokines, such as IL-2, IL-7, IL-10, TNF-α, granulocyte-colony stimulating factor (G-CSF), interferon gamma-induced protein 10 (IP-10; CXCL10), and monocyte chemotactic protein-1 (MCP-1)." (PMID 33251234, 2020). "Concordantly, for downstream genes of AP-1, the expression levels of some chemokine genes (e.g., CCL2, CXCL1, CXCL2, and CXCL10) were downregulated, while the expression levels of immune negative regulation genes (e.g. BCL3, NFKBIA, SOCS3, and TNFAIP3) were upregulated during the COVID-19 recovery." (PMID 33361761, 2020). "As for CXCL10, it can be advocated that an initial more robust TH1 response with monocytes/macrophage over activation in COVID-19 patients, as compared to non-COVID-19 patients, could lead to a subsequent IL-10 overproduction in order to limit T cell responses." (PMID 33272291, 2020). "Thus, our preclinical data in our model do not support targeting CXCL10 in severe COVID-19." (PMID 39803542, 2024). "Our findings reveal that CRP, SAA, VCAM-1, CXCL10, CCL22 and IL-10 levels are promising biomarkers for COVID-19 disease severity, suggesting that plasma inflammatory mediators could be used as warning indicators of COVID-19 severity, aid in COVID-19 prognosis and treatment." (PMID 35958594, 2022). "CXCL10 levels were significantly greater in severe SARS-CoV-2-positive patients than in mild or moderate patients, implying that CXCL10 could be a useful biomarker for distinguishing between mild/moderate and severe COVID-19 patients and predicting disease severity." (PMID 35958594, 2022). "As the known CXCR3 ligands, CXCL9, CXCL10, and CXCL11, are predominantly induced by IFNγ, the presence of this CXCR3-expressing CD11b+CD14+ monocyte subset may be mechanistically related to the synchronous increase in the IFNγ-producing CD4+ T cell subset in our convalescent COVID-19 cohort." (PMID 34113347, 2021). "Among 48 cytokines/chemokines, evaluated by multiplex analysis in patient plasma, 6 (IL-6, CXCL-10, HGF, MIG, MCP-1, and G-CSF) were identified as highly significant in COVID-19 patients compared to non-COVID-19 respiratory disease controls (p-value < 0.0001)." (PMID 37685858, 2023). "Remarkably, COVID-19 patients requiring intensive care unit (ICU) admission presented higher levels of CCL2, CXCL10, IL-2, IL-7, IL-10 and TNF-α than non-ICU patients, hinting the linkage between the cytokine storm and COVID-19 deterioration." (PMID 37251383, 2023). "The diminished abundance of E. rectale comes with the negative correlation to C-X-C motif ligand 10 (CXCL10) and tumor necrosis factor-alpha (TNF-α), two inflammation markers that indicate the origination of immune response at the early stage of COVID-19." (PMID 37743871, 2023). "Another study showed that COVID-19 convalescents at 4 months post infection had higher levels of IFN-β, IFN-λ1, CXCL9, CXCL10, IL-8, and sTIM-3, regardless of symptoms, compared to uninfected controls." (PMID 37077911, 2023). "Analysis of this larger sample set revealed that CXCL10 and CXCL11, but not CXCL9, were significantly upregulated in post-COVID-19 BAL compared with HC BAL." (PMID 35151371, 2022). "In contrast, there was a negative correlation between CXCL10 and CXCL11 levels and the percentage of CXCR3+ ILCs in COVID-19 patients." (PMID 35159352, 2022).
COVID-19 (continued). "Mostly, markers of inflammation such as IL-6, IL-10, CXCL10 (also known as IP10), CXCL11, CCL2, CCL7, CCL8, PD-L1, and IL-18R1 were increased at the early stage of COVID-19 in ICU patients compared to non-ICU ones." (PMID 35269564, 2022). "Serum CXCL9, CXCL10, CXCL11, and CXCR3 levels were significantly higher in patients with severe COVID-19 than in those with non-severe COVID-19; were higher in both patient groups than in the control group; and were higher in patients who died than in those who survived." (PMID 37493737, 2023). "One of the first studies to evaluate the serum cytokine storm in COVID-19 patients showed that several pro-inflammatory mediator levels, such as TNFα, IL-2, IL-7, IL-10, G-CSF, CXCL10, CCL2 and CCL3, were increased in ICU (n = 13) compared to non-ICU COVID-19 patients (n = 28)." (PMID 36941580, 2023). "Also, those COVID-19 patients in hospitalization had higher CCL2, CXCL10, and TNF-α than those who had a non-hospitalized and less severe condition." (PMID 35159388, 2022). "Concentrations of select chemokines (CXCL8, CXCL10, CCL2, CCL3, CCR1) and complement factors (C2, C9, CFD, C4BPA, C5AR1, CR1) were examined at mRNA and protein levels with regard to a COVID-19 course (ICU vs. non-ICU group) and CMV status at different time intervals." (PMID 36232655, 2022). "In conclusion, our study demonstrates that BLC/CXCL13, sCD30, MCP-2/CCL8 and IP-10/CXCL10 are specifically and individually upregulated in symptomatic COVID-19-positive patients but not in patients suffering from other respiratory infections with similar symptoms." (PMID 34540715, 2021). "Interestingly, pro-inflammatory cytokines—such as IFN-gamma, TNF, IL-23, IL-15, IL-21 and IP-10/CXCL-10—were detected both in the sera of severe ICU hospitalized and of non-hospitalized COVID-19 patients." (PMID 33019628, 2020). "COVID-19 patients had lower levels of most classical inflammatory cytokines (G-CSF, CCL20, IL-1β, IL-2, IL-6, IL-8, IL-15, TNF-α, TGF-β), but higher plasma concentrations of CXCL10, GM-CSF and CCL5, compared to non-COVID-19 patients." (PMID 33272291, 2020). "Clinical evaluation of 41 COVID-19 patients (Non-ICU: 28 and ICU: 13) for over 26 chemokines and cytokines revealed increased levels of 16 of them such as IL-1β, IL-1RA, IL-17, IL-8, IL-9, IL-10, basic FGF, G-CSF, GM-CSF, IFN-γ, CXCL10, CCL2, CCL3, CCL4, PDGF, TNF-α." (PMID 33335518, 2020).
viral infection (417 papers, 2007 to 2026). "As a proinflammatory chemokine, CXCL10 can either be protective or pathogenic in viral infections, often correlating with disease severity in respiratory syndromes such as SARS and MERS." (PMID 40459260, 2025). "CXCL10 has been shown to exhibit both protective and pathogenic functions in response to various viral infections, depending on the type of infection." (PMID 39844283, 2025). "The two interferon-induced cytokines most significantly associated with viral infection were CXCL10 (p=2×10−5) and TRAIL (p=1·71×10−5)." (PMID 36586415, 2023). "Elevated levels of CXCL9 and CXCL10 are linked to the Th1 immune response due to bacterial and virus infection." (PMID 37528399, 2023). "CXCL10 is a chemokine that is involved in the recruitment of T cells and plays a role in the pathogenesis associated with several viral infections." (PMID 38058490, 2023). "Markers of the intensity of the viral infection (CXCL10, CCL22) were associated with response, suggesting that the downstream effects of viral replication contributed to antitumor immunity and potentiated the activity of pembrolizumab." (PMID 36445410, 2023). "The role of Cxcl10 has been implicated to play a role in various types of viral infections, such as respiratory syncytial virus (RSV) and dengue virus (DENV)." (PMID 37963152, 2023). "Several studies demonstrated earlier that the expression of chemokines, such as Ccl2, Ccl3, Ccl4, Ccl5, and Cxcl10, during viral infection is associated with enhanced trafficking of leukocytes into the brain." (PMID 34379515, 2021). "As expected, pro-inflammatory genes (e.g., Ifnb1, MCP-1/Ccl2, Cxcl10) associated with a response to viral infection were most prominently upregulated in H3N2 and H5N1 infected mice, as evident in gene ontology (GO) analyses." (PMID 32231671, 2020). "CXCL10 is a key chemokine responsible for early response to viral infection, is associated inflammation, e.g., asthma and is a biomarker that predicts disease severity and pathogenesis." (PMID 32599823, 2020). "The three immune factors modulated by the EPS of S. thermophilus ST538, IFN-β, IL-6, and CXCL10, have been associated to the protection against viral infections." (PMID 32508770, 2020). "In subjects with moderate-to-severe persistent asthma, viral infection was associated with significant increases in mRNA expression of CXCL10 and MDA5." (PMID 30463560, 2018). "Viral infection was also associated with increased mRNA expression of CXCL10 in subjects with mild persistent asthma." (PMID 30463560, 2018). "In mild persistent asthmatics, viral infection was associated with increased protein abundance of CXCL10, sICAM-1, CCL2, CCL4, CCL5, CCL20 and CCL24." (PMID 30463560, 2018). "In moderate-to-severe persistent asthmatics, viral infection was associated with increased protein abundance of CXCL10, IL-4, sICAM-1, CCL2, CCL20 and CCL24." (PMID 30463560, 2018). "Viral infections were associated with significantly increased mRNA expression of CXCL10, RIG-I and MDA5 and protein expression of all biomarkers tested." (PMID 30463560, 2018). "This chemokine is secreted upon stimulation by type I and II interferons, and a dysfunctional or abolished CXCL10 response has previously been associated with failure of the clearance of virus infections." (PMID 27147736, 2016). "The high levels of TNF-α and CXCL10 have been linked to the persistent severe viral disease in patients with severe acute respiratory syndrome." (PMID 27867373, 2016). "IP10 or (C–X–C motif) ligand (CXCL) 10 is a protein highly associated with the presence of viral infection." (PMID 26257731, 2015). "We also measured serum levels of CXCL10, an epithelial chemokine, and IL-10, since these two cytokines were associated with a poor outcome during viral infection and particularly SARS-CoV acute respiratory infection." (PMID 24551142, 2014).
viral infection (continued). "Previously, CXCL10 has been associated with severe viral disease supporting a role for CXCL10 in severe CHIKV disease." (PMID 21858242, 2011). "Furthermore, CVB3-stimulated microglia produced pro-inflammatory cytokines and chemokines, including Il-6, Ccl5, and Cxcl10, underlining their crucial role in orchestrating immune responses during viral infection." (PMID 41503211, 2026). "CXCL10 plays a key role in the development of respiratory symptoms in viral diseases (the population of Yakutia is more susceptible to respiratory diseases and viral infections according to statistics)." (PMID 39769502, 2024). "Experiencing cold symptoms with a PCR-positive viral infection (S+/V+) was associated with increased CXCL10 levels compared to S+/V- cases (Kruskal-Wallis test with Dunn's multiple comparison, p < 0.0001) and S-/V- cases (Kruskal-Wallis test with Dunn's multiple comparison, p = 0.0001)." (PMID 38756971, 2024). "Additionally, CXCL10 levels were associated with the extrahepatic manifestations observed with this viral infection." (PMID 36366543, 2022). "CXCL10 could be protective or pathogenic in viral infections depending on the host’s immune status and the type of viral infection." (PMID 36366543, 2022). "Specific markers of a viral infection such as CXCL10/IP-10, macrophage activation such as sCD14, or HCMV encoded microRNAs may be better markers of HCMV activity than IgG level or CRP concentration, however, more research is needed to answer this question." (PMID 34493708, 2021). "CXCL10 is a chemokine that acts as a chemotactic factor attracting T cells to the site of the infection, and its levels are highly associated with the presence of viral infection." (PMID 34361973, 2021). "Raised CCL and CXCL10 levels were associated with the severity of virus infection." (PMID 32063887, 2019). "The induction of pro-inflammatory cytokines such as COX-2, TNF, IFNs, IL27 and CXCL10 is essential for the host immune response during virus infection, but inappropriately sustained induction causes cytokine-storms, which are associated with a wide variety of infectious diseases." (PMID 24138989, 2013). "In addition to its protective role during the viral infection, CXCL10 may enhance the severity of virus infection and cause neuronal apoptosis and calcium dysregulation and enhance autoreactive lymphoproliferation and brain injury." (PMID 22393386, 2012). "CXCL9 and CXCL10 were identified among DEGs and are host response factors to viral infection downstream of IFNγ." (PMID 41516395, 2026). "CXCL9 and CXCL10 are type 2 interferon-inducible chemokines secreted by macrophages in response to viral infection." (PMID 41516395, 2026). "IFNγ-inducible chemokines CXCL9 and CXCL10 are sourced from pro-inflammatory M1 macrophages in models of viral infection." (PMID 41516395, 2026). "We also noted that the mRNA levels of IFNB, ISG56, RANTES, and CXCL10 in PDCD10-knockdown cells were increased after viral infection." (PMID 41296880, 2025). "Our prior work showed that viral infection is a much stronger driver of nasal mucosal CXCL10 than common upper respiratory bacteria, ruling out one important potential confounder." (PMID 40543450, 2025). "In viral infections, CXCL10 supports effective antiviral defenses, while in OA, its aberrant signaling contributes to chronic inflammation and tissue destruction." (PMID 39836329, 2025). "The results showed that, after RNF149 knockdown, cells produced higher levels of Cxcl10 and Mx1 following viral infection." (PMID 40245000, 2025). "Further detailed studies should be conducted to determine the effects of ISG56 on CXCL10 expression following viral infections." (PMID 38923445, 2024). "IP-10, also known as CXCL10, is a chemokine that’s rapidly and transiently induced following vaccination and various viral infections." (PMID 38572318, 2024).
viral infection (continued). "First, we compared the expression of the antiviral IFN-β gene and the antiviral IFN-stimulated gene CXCL10, following viral infection under normoxia and hypoxia." (PMID 38670937, 2024). "The CXCL10 expression was significantly upregulated upon viral infection in both of the young and mid‐aged mice groups." (PMID 38098255, 2024). "CXCL10 was induced 90-fold upon wild-type virus infection, and this was reduced in the SARS-CoV F70S-infected group." (PMID 38527094, 2024). "In viral infections, CXCL10 contributes to lymphocyte activation, facilitates migration, and promotes the infiltration of specific T cell and NK cell subsets to infection sites." (PMID 38686377, 2024). "Sertoli cells are known to produce CXCL10 in response to viral infection, which triggers cell apoptosis of spermatogenic cells through activation of caspase 3, and their premature displacement from the seminiferous epithelium." (PMID 39621805, 2024). "Other chemokines, such as CXCL10, play a crucial role in inflammation, particularly in the context of viral infections." (PMID 38686377, 2024). "Strong IFN signaling responses observed in acute viral infection are often accompanied by induction of genes associated with cell stress (DDIT3/CHOP), apoptosis (PMAIP1/Noxa), and general inflammatory chemokines (CXCL10, CXCL12, and CCL5)." (PMID 38440980, 2024). "Given the validated role of CXCL10 in viral infection, tumor immunology, and autoimmune arthritis, the balance between CXCL10 and its processing enzymes in inflamed tissues is pivotal for fine-tuning the effects of CXCL10 in (patho)physiological settings." (PMID 38308278, 2024). "C-X-C motif chemokine ligand 10 (CXCL10) is involved in proinflammatory signal pathways, including chemotaxis, differentiation, and activation of immune cells, and immune response to viral infections." (PMID 37795081, 2023). "CXCL10 is a marker of the severity of viral infection and facilitates recruitment of T cells, natural killer cells, macrophages, and dendritic cells." (PMID 36445410, 2023). "CCL2 and CXCL10 play proinflammatory roles in viral infections by stimulating the activation and migration of immune cells to the sites of viral replication including the brain." (PMID 36890518, 2023). "The secretion of CXCL10—a crucial chemokine in viral infections—is induced by many types of interferons, including IFNβ." (PMID 37371616, 2023). "CXCL10 controls viral infection and has a role in innate immune response via the recruitment and activation of natural killer cells and exerts a potent chemotactic effect on activated T lymphocytes by binding CXCR3." (PMID 38006039, 2023). "Using the automated assay, the ROC curve for prediction of viral infection from nasopharyngeal CXCL10 concentration had an area under the curve of 0·964 (95% CI 0·92–1·00)." (PMID 36586415, 2023). "Increased levels of CXCL10 and IFN-γ have been reported in severe thrombocytopenia caused by viral infections, and malaria." (PMID 36178979, 2022). "In our study of 16HBE cells infected with SARS-CoV-2, we found that the level of CXCL10 transcription increased gradually with virus infection progression but that relative expression of ISG15, NF-κB, IFN-α and IFN-β increased within 6 h and then decreased." (PMID 36560452, 2022). "It has been reported that interferon can significantly trigger the production of many interferon-induced genes (IFIT1, IFITM3, MX-1, OASL, ISG15, PKR, GBP1, Viperin, BST2, IRF-1, and CXCL10), which play key roles in the resistance to viral infection." (PMID 36337195, 2022). "On the other hand, mAbs which promoted viral infection of human macrophages enhanced systemic IL-18, IL-1RA, and CXCL10 particularly in early disease." (PMID 35483404, 2022). "As further evidence for TRIM41-mediated virus-triggered interferogenic response, we found that TRIM41 deficiency impaired the induction of interferon-stimulated genes (ISG), such as Cxcl10, Ccl5, and Ifi202b, by virus infections." (PMID 33640899, 2021).